AR (androgen receptor)
Diseases named in the same sentence as AR in open-access papers (continued):
Sharing a sentence is not in itself a finding about the gene and the disease.
breast carcinoma (continued). "AR was negatively correlated with the immune microenvironment in patients with HER2+HR− nonmetastatic breast cancer." (PMID 37085500, 2023). "Interestingly, AR and stromal SDC1 expression are altered concomitantly by subjecting breast cancer to agonists for the ER, PR, and/or AR in an animal model." (PMID 36980680, 2023). "In TNBC MDA-MB-231 cells, the expression of the AR is not the highest among other breast cancer subtypes, but it still indirectly influences the face of PD-L1, which regulates cell progression." (PMID 37681860, 2023). "A total of 1231 eligible cases of breast cancer were enrolled from January, 2018 to December, 2021, of which 917 cases were AR positive and 314 cases were AR negative, and the AR positive rate was 74.5%." (PMID 37099044, 2023). "Moreover, a cross-talk between this pathway and caspase-8 was also observed for Exe in sensitive and resistant breast cancer cells when autophagy, PI3K, and AR were targeted." (PMID 37173983, 2023). "Data support a potential role for this protein as a single biomarker for classification of breast cancer subtypes, since its expression is indicative of a negative receptor status/resistance to receptor-dependent treatments with respect to ER, PR, AR and HER2 in breast cancer." (PMID 37306503, 2023). "To better elucidate the role of AR and BAD cooperation, we investigated if our findings may have an impact on the outcome of ER+ breast cancer patients." (PMID 37686282, 2023). "New insights into the association between AR and immune infiltration in HER2+ nonmetastatic breast cancer can be explored to facilitate the stratification of prognosis and provide a reference for individualized treatment." (PMID 37085500, 2023). "Observational studies have demonstrated that ACSL4 mRNA expression is inversely correlated with ER, AR and HER2 expression in both breast cancer cell lines and tumor samples, and is most highly expressed in TNBCs that fall into the category of claudin-low and basal-like cancers." (PMID 37306503, 2023). "In HER2+HR− nonmetastatic breast cancers, AR was negatively correlated with the immune microenvironment." (PMID 37085500, 2023). "The largest among these studies, which was performed on 2171 patients in the US between 1976 and 1996 using the AR441 antibody, reported AR expression (≥1%) in 91% of Luminal A, 68% of Luminal B, 59% of HER2-postive, and 32% of triple negative primary breast cancers." (PMID 37345085, 2023). "The variability in frequency of the AR expression in TNBC is mostly due to the lack of standard assay used for breast cancer and the use of different assay cutoffs." (PMID 35711833, 2022). "In this study, we found that AR influenced the long–term survival of patients with luminal B (HER–2 negative) breast cancer, with an optimal cutoff value of 65%." (PMID 36556209, 2022). "Androgen receptor (AR) is not routinely assessed in breast cancer patients, despite being expressed in approximately 60–70% of all breast cancer tumors." (PMID 35761157, 2022). "In line with this, an AR agonist, but not an antagonist, was shown to inhibit the proliferation and growth of ER-positive breast cancer cells, patient-derived tissues, and patient-derived xenografts (PDX)." (PMID 35761157, 2022). "Enzalutamide and abiraterone were shown to sensitize breast cancer cells to CTL-mediated lysis independent of detectable AR expression." (PMID 36497086, 2022). "Further, our results suggest that methods of targeting AR signaling using pharmacologic AR antagonists and/or blocking androgen production with CYP17 inhibitors are insufficient to alter the radiation response in vitro in AR+/ER+ breast cancer models." (PMID 35618789, 2022). "However, AR functions as a tumor promoter in ER-ve breast cancers, including HER2 + ve and triple-negative (TNBC) breast cancers, serving as a poor prognostic factor." (PMID 35053220, 2022).
breast carcinoma (continued). "Owing to the function of CR1447 as an AI and AR-modulator, patients with metastatic or locally advanced ER+/HER2− including also ER+/HER2− AR+ breast cancer and triple-negative breast cancers (TNBC) AR+ breast cancer were considered suitable candidates for a phase II trial." (PMID 37435469, 2022). "At present, two powerful PROTAC candidates have entered phase 1/2 clinical trials developed by the Arvinas company, namely, ARV-110 targeting androgen receptors (AR) for treating prostate cancer, and ARV-471 targeting estrogen receptors (ER) for treating breast cancer." (PMID 36059670, 2022). "In patients with luminal B (HER–2 negative) breast cancer who underwent neoadjuvant therapy, AR expression level alone was not an influencing factor for prognosis, whereas AR/ER > 1.06 and residual tumor Ki67 > 23% were risk factors for DFS." (PMID 36556209, 2022). "Targeting AR by the shRNA and inhibitor could effectively suppress HER2 + ve/ER-ve breast cancer cell growth in vitro and in vivo." (PMID 35053220, 2022). "Clinical PROTAC degraders of AR and ER with minor off-target toxicities harbor favorable pharmacokinetic profiles and are well-tolerated by heavily pretreated patients with advanced/refractory prostate or ER+/HER2- breast cancer, respectively." (PMID 36499765, 2022). "However, it is not clear whether ACK1 and AR protein expression is associated in breast cancer." (PMID 35768871, 2022). "While previous work has demonstrated a role for tamoxifen or fulvestrant in the radiosensitisation of ER+ breast cancer models in vitro and in vivo, the role of AR and ER together and the impact on radiosensitisation has not been assessed." (PMID 35618789, 2022). "Together these findings suggest that AR inhibition alone is not sufficient to radiosensitise AR+/ER+ breast cancer models." (PMID 35618789, 2022). "While our previous data suggest that inhibition or degradation of ER results in radiosensitisation, here we demonstrate that ER inhibition is not uniformly sufficient to radiosensitise AR+/ER+ breast cancer models." (PMID 35618789, 2022). "To confirm our speculations, we downloaded RNA-seq data and clinical information for breast cancer from The Cancer Genome Atlas (TCGA) database and analyzed it for ZMIZ2 expression and the correlation between ZMIZ2 and AR." (PMID 35101047, 2022). "The study contributes to the early screening of patients with a poor prognosis of luminal B (HER–2 negative) breast cancer and provides a basis for studies on AR–targeted therapies." (PMID 36556209, 2022). "Of 61 TNBC cases analysed, 37.7% were AR positive and 62.3% were AR negative, making the latter to become quadruple negative breast cancers." (PMID 36405944, 2022). "We examined the levels of AR protein in the three different TNBC cell lines (BT549, MDA-MB-453, and SUM159PT) and compared these to AR protein in the ER+/AR+ MCF7 breast cancer cell line by 1D western blots normalizing the AR band intensity to that of GAPDH as a loading control." (PMID 36584207, 2022). "Our data show that the expression of POLR3G in breast cancer samples was negatively correlated with that of eight out of ten genes (GATA3; XBP1; AGR2; SIDT1; AR; SPDEF; FOXA1; MLPH) in a list of signature genes most differentially expressed in luminal A compared to basal-like tumors." (PMID 36497214, 2022). "The presence of an androgen receptor subdivided TNBC into quadruple-negative breast cancer and AR-positive TNBC, the latter of which harnessed a different dependency on the androgen receptor, which was more ubiquitously expressed than ER and PR." (PMID 35847875, 2022). "In HER2–positive breast cancer, the expression of AR is elevated, regardless of the status of hormone receptor." (PMID 36556209, 2022). "In ERα-ve breast cancer patients, including HER2+ve and TNBC, the AR shows oncogenic effects." (PMID 36499670, 2022).
breast carcinoma (continued). "These activities result in distinct molecular and phenotypic profiles in AR-positive TNBC (AR+TNBC) compared with AR-negative TNBC or quadruple-negative breast cancer (QNBC)." (PMID 35203574, 2022). "Breast cancer (MCF-7) and PCa (22Rv1 and MDA PCa 2b) cell lines that express considerable levels of AR were used as in vitro cell line models to study the miR-99b-5p involvement in AR-mTOR axis." (PMID 36077039, 2022). "We aimed to investigate the effect of the androgen receptor signaling pathway-related long non-coding RNAs (ARSP-related lncRNAs) on the process of subtype classification and the tumor microenvironment (TME) of breast cancer (BRCA)." (PMID 36450882, 2022). "It is hypothesized that the androgen receptor plays a role as an oncogene in TNBC, mediating tumour cell growth, contrary to its anti-oestrogenic and growth-inhibitory influence in ER+ breast cancer." (PMID 35877237, 2022). "Androgen receptor (AR) is widely expressed in breast cancer, but there is no clear conclusion about its function and correlation with prognosis in luminal B breast cancer." (PMID 36556209, 2022). "In addition to regulating ESR1 gene expression, FOXA1 acts as a pioneer factor for AR expression not only in prostate but also in breast cancer, and, TNBCs that lose metastatic potential co-express FOXA1 and AR." (PMID 36171192, 2022). "Similarly, two additional nuclear receptors, the androgen receptor (AR) and the estrogen receptor (ER), have been shown to suppress EMT in prostate and breast cancer cells, respectively." (PMID 35605663, 2022). "This is in contrast with previous work suggesting that AR inhibition, independent of ER status, results in radiosensitisation in AR+ breast cancer models." (PMID 35618789, 2022). "On the other hand, enobosarm, a nonsteroidal selective androgen receptor modulator/agonist, inhibits in vivo tumor growth of ERα-positive breast cancers." (PMID 37435447, 2022). "“Androgen receptor driven transcription in molecular apocrine breast cancer is mediated by FoxA1” was the article with the highest betweenness centrality, also showing a high correlation between ARs and FOXA1 in molecular apocrine breast cancer." (PMID 35800434, 2022). "Fortunately, the expression of androgen receptor (AR) is positively correlated with RB, which promotes cyclin D activation, suggesting that CDK4/6 inhibitors have great potential in the treatment of HER2-negative breast cancer with AR-positive." (PMID 35311116, 2022). "In contrast, GT0918 showed no antitumor activity in AR-negative MDA-MB-468 breast cancer xenograft tumors." (PMID 34392453, 2021). "The breast cancer subnetwork is found to contain (i) valid biomarkers including PIK3CA, PTEN, BRCA1, AR and EGFR; (ii) validated drug targets TOP2A, CDK4, HDAC1, IL6, BRCA1, HSP90AA1 and AR; (iii) synergistic drug targets EGFR and BIRC5." (PMID 35053185, 2021). "It has also been shown to promote the growth of breast cancer cells in estrogen receptor-negative (ER−)/AR-positive (AR+) patients." (PMID 35069211, 2021). "Indeed, in this study, the patient in case 1 who had rapid progression was AR positive and likely represented a luminal androgen receptor (LAR) subtype of breast cancer." (PMID 34667258, 2021). "Furthermore, in ER+ve breast cancer models, dihydrotestosterone (DHT)-mediated activation of AR has been shown to inhibit ER-α signaling and cell cycle progression through a reduction in CCND1 transcription." (PMID 33777765, 2021). "Androgen receptor (AR) is a transcription factor activated by androgens, such as dihydrotestosterone (DHT) in women and testosterone in men and is expressed at various levels across all breast cancer subtypes." (PMID 34736512, 2021). "In gastric cancer, EGFR overexpression correlated significantly with AR overexpression, and a negative correlation was observed in breast cancer." (PMID 34681618, 2021).
breast carcinoma (continued). "The clinical and biological significance of AR expression in breast cancer is not straight forward due to variations in both the levels of AR as well as the intrinsic differences among the multiple subtypes of breast cancer." (PMID 34234742, 2021). "On the other hand, the role of the AR in ERα negative (ERα-) breast cancer is controversial and its prognostic value remains uncertain." (PMID 35008851, 2021). "In multiple non-LAR breast cancer subtypes, relatively low AR expression depended on AR for proliferation, migration, and invasion." (PMID 33915941, 2021). "KLK3 and AZGP1 expression were not strongly correlated with AR expression in all breast cancer subtypes." (PMID 34736512, 2021). "Previous studies have shown that approximately 50% of PD-L1 transmembrane proteins in breast cancer with androgen receptor (AR)-negative prevalence and TNBC cells express PD-L1, whose receptor is PD-1, and also bind PD-L2 as other ligands, and express CTLA-4." (PMID 34198652, 2021). "We have not confined ourselves to ER positive, HER2 negative breast cancer alone as the prognostic utility of high AR/ER ratio is well established within this subtype." (PMID 34234742, 2021). "Thus, the expression levels of AR, miR-185, miR-205, and miR-21 can serve as markers to predict cancer spread to the lymph node in luminal B- and HER2-positive subtypes of breast cancer." (PMID 32373367, 2020). "In breast cancer cell lines that lack AR, however, treatment with seviteronel does not lead to radiosensitization, suggesting the effect is mediated through the androgen receptor." (PMID 32117061, 2020). "In contrast, preclinical studies have shown that in ERα-negative, HER 2-positive breast cancers, AR promotes tumor growth through the AR/FOXA1/β-catenin complex which binds to the HER 3 gene, thereby inducing cancer cell proliferation." (PMID 31952272, 2020). "Since HCC70 breast cancer cells lack functional ER, known to mediate oncogenic effects of NIC intracellularly, we examined expression levels of glucocorticoid receptors (GR) and androgen receptor (AR)." (PMID 33414685, 2020). "We had previously shown that TTP represses the transactivation activity or different steroid nuclear receptors including ERα, progesterone receptor, androgen receptor and glucocorticoid receptor without affecting their protein levels in breast cancer cells." (PMID 33117284, 2020). "Interestingly, apocrine carcinoma, a special type of breast cancer, typically exhibits the immunohistochemical profile of TNBC with AR positivity." (PMID 32697770, 2020). "In advanced breast cancers, AR does not seem to predict the efficacy of first-line antiestrogen endocrine therapy, whereas progesterone receptor and Ki67 were shown to be more potent predictors." (PMID 31952272, 2020). "In addition, AR is commonly enriched in breast cancers overexpressing HER2, indicating a role for AR in activation of HER2 and Wnt signaling." (PMID 33062889, 2020). "Therefore, this study and our study showed that KLF4 represses DYRK2 gene expression in CML, while in breast cancer, DYRK2 prevents androgen receptor-mediated activation of the KLF4 gene." (PMID 33067577, 2020). "Together these data from multiple cancer models suggest that AR has non-genomic functions affecting tumor growth both in prostate and breast cancer which warrant further investigation." (PMID 33062889, 2020). "Factors other than AR may include KLF4 and c-MYC, which were found to be involved in breast cancer stem cell maintenance." (PMID 32781788, 2020). "AR was not a significant prognostic factor for overall survival in any of the breast cancer subtypes." (PMID 32290220, 2020).
breast carcinoma (continued). "Among TNBC samples with a PIK3CA-AKT1-PTEN pathway alteration, 1,192 (78.6%) were negative for AR expression by IHC (i.e., quadruple-negative breast cancer)." (PMID 32983983, 2020). "The function of AR in breast cancer appears to be dependent upon its co-expression with ER, as there is evidence for varying effects of AR on the growth of breast cancer cells in the presence or absence of ER." (PMID 33062889, 2020). "In addition, high expression of AR and PTEN is correlated with better clinical outcomes for breast cancer patients." (PMID 33062889, 2020). "Male breast cancer was more often of ductal type, grade II and a very high proportion were ER and AR positive and HER2 negative." (PMID 32108307, 2020). "Our data suggest that dual targeting of AR and SUMO might have clinical and therapeutic relevance in the ET-R HR+ BCa subset of breast cancer." (PMID 32948192, 2020). "The objectives of this study were to describe AR and FOXA1 expressions in feline mammary carcinomas (FMCs), their prognostic value, and if their coexpression could define a “luminal-AR” subtype of triple-negative mammary carcinomas in cats." (PMID 31888566, 2019). "Although quite a few studies try to show the role of AR in breast cancer cells, the function of AR in breast cancer is not totally clear." (PMID 31126320, 2019). "Also in the breast cancer cell line MDA-MB-453, treatment with the AR-agonist CI-4AS-1 resulted in a significant downregulation of miR-125b and miR-100 and induced the expression of their target gene metalloprotease-13 (MMP13)." (PMID 31744106, 2019). "Likewise, multiple antibodies have been used to measure AR protein expression, but the AR441 antibody has been used in the majority of studies evaluating AR as a prognostic marker for breast cancer." (PMID 30795773, 2019). "AR is found to be expressed by immunohistochemistry in 60–80% of breast cancers, less frequently in estrogen receptor-negative as compared to estrogen-receptor positive tumors." (PMID 31245286, 2019). "AR would rather be famous as the potential target in the therapy for triple negative breast cancer (TNBC), which does not express ER, PR, and HER2/neu and tends to be more aggressive than other subtypes of breast cancers." (PMID 31151151, 2019). "Despite the non-significantly lower efficacy of letrozole in AR−/ER+ breast cancers, survival outcomes among those receiving letrozole monotherapy were superior to those among individuals receiving tamoxifen regardless of tumor AR expression." (PMID 30795773, 2019). "The last known subtype, luminal androgen receptor (LAR), is found to overlap with the molecular apocrine group (“molecular apocrine breast cancer”/MABC) and is enriched in genes regulating hormone signaling, in particular androgen signaling and synthesis (AR, FOXA1, KRT18, XBP1)." (PMID 30871273, 2019). "AR also enhanced MYC transcriptional activity by phosphorylating MAD1 and promoting activation of the HER2/HER3 signaling pathway, leading to increased levels of MYC/MAX heterodimers that ultimately promoted breast cancer growth." (PMID 31413736, 2019). "Thus, we tested the combination effect of an AR antagonist (enzalutamide) and USP14 inhibitor (IU1)/siRNA in breast cancer cells." (PMID 31126320, 2019). "Despite this published data, the biological role of the AR expression in breast cancer is still not clear." (PMID 31728025, 2019). "The basal-like or triple-negative form of breast cancer refers to tumors not expressing the ER, PR, AR and HER2 genes." (PMID 31731625, 2019). "The expression of EGFR was alongside the expression of other prominent breast cancer biomarkers such as the androgen receptor and Ki67 protein (the cellular marker for cell proliferation), thus suggesting EGFR is another therapeutic target for breast cancer treatment." (PMID 31064156, 2019).